TRIM28 (tripartite motif containing 28)
Diseases named in the same sentence as TRIM28 in open-access papers (continued):
Sharing a sentence is not in itself a finding about the gene and the disease.
breast cancer (continued). "Therefore, it seemed more appropriate to analyze the impact of TRIM28 gene depletion on breast cancer stem cell population in mouse model in vivo." (PMID 27845900, 2017). "However, the exact direct mechanism of TRIM28-mediated regulation of CSC metabolism in breast cancer remains to be elucidated." (PMID 27845900, 2017). "We believe that our findings may shed new light on the epigenetic hemostasis of breast cancer stem cells and pave the way to novel and more effective therapies that target TRIM28 protein in breast tumors." (PMID 27845900, 2017). "To determine the correlation between TRIM28 levels and breast cancer development, we collected invasive ductal carcinoma specimens from 33 human breast cancer patients and 11 adjacent normal tissues in Southwest Medical University Affiliated Hospital in China with informed consent." (PMID 27412325, 2016). "Overexpression of TRIM28 in breast cancer cell line promotes cell migration and invasion." (PMID 27412325, 2016). "Therefore, identification of specific factors linking to this axis will not only enhance our understanding the roles of TRIM28 in breast cancer development but also provide more targeting points for breast cancer therapies." (PMID 27412325, 2016). "Our study revealed a novel mechanism in breast cancer cells that TRIM28 enhances metastasis by stabilizing TWIST1, suggesting that targeting TRIM28 could be an efficacious strategy in breast cancer treatment." (PMID 27412325, 2016). "miR-512-5p, miR-491, miR-140-3p, and miR-548ac have been found to reduce the levels of endogenous TRIM28 in gastric cancer (GC), glioblastoma, breast cancer (BC), and acute myeloid leukemia (AML) cells." (PMID 39100077, 2024). "A significant elevation in TRIM28 gene expression has been noted across all four intrinsic subtypes of breast cancer (BC), as well as in BC metastases, in comparison with normal tissue." (PMID 39534556, 2024). "Furthermore, a series of researches on function and mechanism are required to verify the effect of TRIM28 on the migration and proliferation of BC cells and to explore the upstream and downstream molecular mechanisms of TRIM28 in promoting breast cancer progression." (PMID 33817325, 2021). "The expression and function of TRIM28 in breast carcinoma (BC) remain unclear." (PMID 33817325, 2021). "Therefore, we proposed that TRIM28 depletion in breast cancer cell lines may inhibit self-renewal of CSCs and sensitize the cells to standard therapies." (PMID 27845900, 2017). "To determine whether TRIM28 plays an important role in breast cancer metastasis, we first compared the mRNA levels of TRIM28 in different breast cancer cell lines (MDA-MB-231, MDA-MB-435, T47D, MCF7 and BT549) with that of non-cancerous epithelial cell line MCF10A." (PMID 27412325, 2016). "In previous studies, we have confirmed that BRD7 is a highly unstable protein in breast cancer, and TRIM28‐mediated BRD7 instability is a significant mechanism contributing to the onset and development of breast cancer." (PMID 41510594, 2026). "TRIM28 expression is high in MDA-MB-231, MDA-MB-435, T47D, MCF-7, and BT549 breast cancer cell lines and is involved in the development and metastasis of breast cancer." (PMID 40733287, 2025). "TRIM28 is involved in the transcriptional activation of the EMT program, which mediates the stem cell-like phenotype of breast cancers." (PMID 36674511, 2023). "In estrogen receptor- positive breast cancer cell line MCF7, TRIM28 interacts with histone methyl transferase Enhancer of Zeste Homolog 2 (EZH2) and SWI/SNF to activate the expression of genes that promote CD44hi/CD24lo mammosphere formation." (PMID 36756159, 2023). "Taken together, these results demonstrate that hypoxia induces TRIM28- and KU70/86-dependent, but ATM- and DNA damage-independent, activation of DNA-PKcs, which is required for HIF target gene expression in human breast cancer cells." (PMID 35031618, 2022).
breast cancer (continued). "Hypoxia-induced occupancy of the ANGPTL4 and PDK1 HREs by TRIM28, KU70, KU86, DNA-PKcs, and HIF-1α was also observed in SUM159 human breast cancer cells." (PMID 35031618, 2022). "Taken together, these data demonstrate that both TRIM28 and DNA-PKcs are required for HIF-dependent regulation of gene expression in human breast cancer cells." (PMID 35031618, 2022). "Here we report that in hypoxic breast cancer cells, HIF-1 recruits TRIM28 and DNA-dependent protein kinase (DNA-PK) to HREs to release paused Pol II." (PMID 35031618, 2022). "In the present study, we uncovered a critical role for TRIM28 and DNA-PK in HIF-1-mediated transcription in hypoxic human breast cancer cells." (PMID 35031618, 2022). "In the MCF7 ER-positive breast cancer cells, EZH2 interacts with subunits of the SWI/SNF chromatin remodeler complex and TRIM28, forming a complex distinct from PRC2." (PMID 33327550, 2020). "Knockdown of TRIM28 resulted in TWIST1 downregulation with concurrent upregulation of E-CADHERIN and downregulation of N-CADHERIN that consequently inhibited breast cancer cell migration and invasion in vitro." (PMID 28851455, 2017). "Recent studies have demonstrated the role of TRIM28 protein in autophagy, a stress-induced process that has been suggested to maintain the CD44+/CD24−/low breast cancer stem-like phenotype." (PMID 27845900, 2017). "We knocked down TRIM28 in both T47D and BT549 breast cancer lines and monitored the effect on E-Cadherin and N-Cadherin by western blotting assays." (PMID 27412325, 2016). "In addition, TRIM28 acts directly with TWIST1 to stabilize it, and then enhances EMT to promote breast cancer metastasis." (PMID 33817325, 2021). "In accordance to this observation, TRIM28 reduction did not change the percentage of CSCs characterized by the CD44+CD24−/low phenotype in vitro in the tested breast cancer cell lines." (PMID 27845900, 2017). "In our studies we observed that TRIM28 downregulation has no impact on cell proliferation and viability in vitro in all tested breast cancer cell lines 24 hours after seeding." (PMID 27845900, 2017). "TRIM28-depleted and non-modified cells (WT) from selected breast cancer cell lines were injected subcutaneously into athymic nude mice (5 × 106 cells/injection site, 12 animals per group)." (PMID 27845900, 2017). "On the other hand, together with the MAGE-A3/6 (Melanoma Antigen member A3, A6), TRIM28 forms a cancer-specific ubiquitinase that regulates the AMPK level in cancer cells, enhancing the oxidative phosphorylation and maintaining stem cell traits of breast cancer." (PMID 33076560, 2020). "Similarly, TRIM28 knockdown did not sensitize breast cancer cells to irradiation in vitro over the dose range of 0-8 Gy." (PMID 27845900, 2017). "Therefore, we conclude that TRIM28 knockdown does not affect cell homeostasis in breast cancer cell lines in vitro." (PMID 27845900, 2017). "In addition, the protein levels of TRIM28 and TWIST1 are not only elevated but also positively correlated with each other, suggesting that TRIM28 and TWIST1 may play important roles in breast cancer development and/or invasiveness." (PMID 27412325, 2016).
lung carcinoma (26 papers, 2014 to 2025). "For example, in early‐stage lung cancer, heightened TRIM28 expression is linked to enhanced overall survival, indicating a potential antiproliferative role within tumor cells." (PMID 39534556, 2024). "Despite a higher positive correlation (Pearson correlation coefficient R ≈ 0.84), we determined several known lung cancer-associated genes with high RS and low |log2FC|, such as TRIM28, APP, ESR1, MYC, and EGFR." (PMID 36229842, 2022). "Furthermore, studies have demonstrated that TRIM28 is implicated in TGF‐β‐triggered EMT in non‐small cell lung cancer cells." (PMID 39534556, 2024). "However, in the early stage of lung cancer, high expression of TRIM28 was also reported to be associated with a better overall survival and mice with liver-specific ablation of TRIM28 showed an increase in hepatic adenoma, particularly in male animals." (PMID 33670160, 2021). "Higher TRIM28 expression was associated with a poorer prognosis in lung cancer and gastric cancer." (PMID 33091876, 2020). "They revealed that TRIM28 overexpression is associated with better overall survival of patients with early-stage lung cancer, suggesting that TRIM28 may also have anti-proliferative activity to some tumor cells." (PMID 30484263, 2019). "In early-stage lung cancer, higher expression of TRIM28 gene is associated with better overall survival, suggesting that TRIM28 may have also antiproliferative activity within tumour cells." (PMID 30974870, 2019). "In early-stage lung cancer higher expression of TRIM28 gene is associated with better overall survival, suggesting that TRIM28 may have also anti-proliferative activity within tumor cells." (PMID 28851455, 2017). "Of note, while TRIM28 is widely studied for its promoting effect on cancer cell proliferation, it can also exert an anti-proliferative role in early lung cancer by inhibiting the transcriptional activity of the E2F family." (PMID 39160596, 2024). "TRIM28 can also exhibit an antiproliferative effect in early lung cancer by inhibiting the transcriptional activity of the E2F family." (PMID 39534556, 2024). "Reducing TRIM28 expression significantly increases the vulnerability of lung cancer cells to 5‐fluorouracil." (PMID 39534556, 2024). "In syngeneic lung cancer models, we evaluated the impact of TRIM28 inhibition on the efficacy of anti-PD-1 therapy." (PMID 37865804, 2023). "Next, we explored the relationship between TRIM28 expression and the clinical characteristics of lung cancer patients in the Kaplan-Meier plotter database." (PMID 33091876, 2020). "Correlation between TRIM28 mRNA expression and prognosis in lung cancer patients with different clinicopathological characteristics, determined via Kaplan-Meier plotter." (PMID 33091876, 2020). "TRIM28 expression was higher in bladder cancer, colorectal cancer, gastric cancer, head and neck cancer, liver cancer, lung cancer and multiple myeloma than in healthy tissues." (PMID 33091876, 2020). "TRIM28 depletion in breast and lung cancer cell lines has been shown to result in increased cell proliferation." (PMID 30543698, 2018). "The most notable component of our work described here is that Trim28 influences TGF-β-induced EMT in lung cancer through transcriptional regulation of multiple epithelial and mesenchymal markers." (PMID 24983967, 2014). "Taken together with our previous work these results suggest a model in which Trim28 is a tumor suppressor early in the transformation process in lung cancer, but in later stages it functions as an oncogene." (PMID 24983967, 2014). "Conversely, ectopic expression of TRIM28 in lung cancer cells had the opposite effect." (PMID 37865804, 2023).
lung carcinoma (continued). "Due to these contradictory observations, the prognostic value of TRIM28 in lung cancer remains unclear." (PMID 33091876, 2020). "Collectively, these data suggest that Trim28 can promote EMT in lung cancer cell lines." (PMID 24983967, 2014). "We found that Trim28 contributes to TGF-β-induced EMT, and that high Trim28 favors EMT suggesting that Trim28 might be a regulator of tumor metastasis, particularly in the later stage of lung cancer development." (PMID 24983967, 2014). "Therefore, we investigated whether targeting TRIM28 in lung cancer could enhance the efficacy of anti-PD-1 therapy." (PMID 37865804, 2023). "Next, we assessed whether TRIM28 alters CXCL1 expression in murine and human lung cancer cell lines." (PMID 37865804, 2023). "TRIM28 regulated E-cadherin and N-cadherin, resulting in EMT in lung cancer cells." (PMID 34722282, 2021). "Tripartite motif containing 28 (TRIM28) protein, a universal co-factor for KRAB-ZFP transcription factors, contributes to EMT and might be important for tumor metastasis in lung cancer." (PMID 33916522, 2021). "To determine whether TRIM28 affects the induced expression of MAGEC2 in tumor cells, we treated MAGEC2-negative human lung cancer cells A549 with demethylating agent 5-aza-2-deoxycytidine (5-aza) in the presence or absence of TRIM28." (PMID 30309319, 2018). "TRIM28 contributes to EMT and might be involved in lung cancer metastasis." (PMID 35008645, 2021). "TRIM28 deficiency impairs TGF-β-induced EMT and decreases cell migration and invasion, and the expression of TRIM28 affects the acetylation of histones on E-cadherin and N-cadherin promoters, suggesting that TRIM28 contributes to EMT and might be important for tumor metastasis in lung cancer." (PMID 33916522, 2021).
gastric cancer (25 papers, 2015 to 2025). A primary or metastatic malignant neoplasm involving the stomach. "In gastric cancer specimens, there was a notable increase in TRIM28 expression in clinical tumor samples, which was associated with poor prognosis, larger tumor size, and increased peritoneal carcinomatosis." (PMID 39768197, 2024). "Although TRIM28 had an increased level in human gastric cancer tissues, it was associated with improved prognosis in clinical sample analysis." (PMID 39768197, 2024). "From the public database, we found that lower TRIM28 mRNA expression was associated with significantly higher overall survival (OS) of ≥150 months in gastric cancer patients." (PMID 34419074, 2021). "For example, in gastric cancer overexpression of TRIM28 and TRIM29 is associated with increased cell proliferation and a poor prognosis in patients." (PMID 30089913, 2019). "Moreover, the upregulation of TRIM28 gene in tumor tissues has been shown in gastric cancer and is associated with poor prognosis; TRIM28 gene overexpression was also detected in peripheral blood of gastric cancer patients." (PMID 28851455, 2017). "In gastric cancer with high TRIM28 expression: TRIM28 stabilizes PD-L1 protein by inhibiting PD-L1 ubiquitination and promoting its SUMOylation; meanwhile, it increases PD-L1 abundance by activating the TBK1 pathway, exacerbating immune evasion." (PMID 40936722, 2025). "Studies have found that TRIM28 abnormally expressed in gastric cancer, colorectal cancer, and non-small cell lung cancer, promotes tumor progression." (PMID 38956267, 2024). "TRIM28 knockdown in gastric cancer cell lines AGS and HGC-27 promoted cell stemness through activation of β-catenin signaling." (PMID 39768197, 2024). "We observed that TRIM28 ablation markedly enhanced the T-cell-mediated destruction of gastric cancer cells." (PMID 37357254, 2023). "Kaplan-Meier survival analysis showed shorter overall survival time (OS) for gastric cancer patients with high expression of lnc-TRIM28-14." (PMID 36690975, 2023). "We then performed qRT-PCR validation of gastric cancer specimens and found that the expression of lnc-RFNG-1 and lnc-TRIM28-14 was significantly increased in gastric cancer tissues with peritoneal metastasis." (PMID 36690975, 2023). "TRIM28 overexpression was also detected in gastric cancer, ovarian cancer, glioma and hepatocellular carcinoma, suggesting that TRIM28 upregulation is a common feature of many epithelial cancers." (PMID 30484263, 2019). "TRIM28 specifically has been found to be increased in gastric cancers, whereas its inactivation in hepatocytes promotes hepatocellular carcinoma in a cell-autonomous manner." (PMID 29481576, 2018). "Among them, the overexpression of TRIM28 in gastric cancer was involved in the progression of cancer, and acted as an independent prognostic factor for poor survival." (PMID 30299268, 2018). "TRIM28 is involved in cancer progression; it is overexpressed in colorectal and gastric cancer and is an independent prognostic factor for poor overall and relapse-free survival." (PMID 27835598, 2016). "TRIM28 is pivotal in maintaining gastric cancer stem cell viability and immune regulation." (PMID 40936722, 2025). "Upregulation of TRIM28 was found in gastric cancer cells and contributed to reduced OS rate." (PMID 39768197, 2024). "Furthermore, TRIM28 has been found to facilitate gastric cancer cell proliferation by the serum response factor/Indoleamine 2,3-dioxygenase (SRF/IDO1) axis, whereby it regulates IDO1 expression by modulating SRF levels." (PMID 39768197, 2024). "TRIM28 promotes gastric cancer progression via its antiapoptotic effects, which leads to EMT." (PMID 36756159, 2023). "TRIM28 is an independent factor for peritoneal dissemination of gastric cancer." (PMID 36756159, 2023).
gastric cancer (continued). "Increased expression of the TRIM28 gene has also been demonstrated in gastric cancer (GC), correlating with unfavorable prognosis 208; Overexpression of the TRIM28 gene has also been identified in the peripheral blood of patients with GC." (PMID 39534556, 2024). "In Epstein–Barr virus (EBV)-associated gastric cancer, EBV-encoded small ribonucleic acid 1(BHRF1) upregulates the expression of SNHG8, which as a sponge of miR-512-5p, leading to increased expression of TRIM28, and promoting malignant progression of the tumor." (PMID 36756159, 2023). "Formation of the NEK9-ROBO1-SLIT2 ternary complex promoted NEK9-mediated phosphorylation of the transcriptional elongation factors, tripartite motif containing 28 (TRIM28) and cortactin (CTTN), which helped to promote metastasis in gastric cancer cells." (PMID 41154634, 2025). "As validated through evidence from patient tissues and in vitro experiments using AGS and MKN45 cell lines, TRIM28 activated the transcription of STAT3, thus triggering the JAK/STAT pathway and promoting gastric cancer cell metastasis." (PMID 39768197, 2024). "Intriguingly, lnc-TRIM28-14 was positively correlated with the expression levels of CD93 and COL4A1 in gastric cancer peritoneal metastasis, suggesting a regulatory relationship between them." (PMID 36690975, 2023). "Overall, we suggest that LOC441461 modulates gene transcription, inducing the malignancy of gastric cancer by interacting with RELA, IRF1, ESR1, AR, POU5F1, TRIM28, and GATA1." (PMID 35267457, 2022). "The interaction of the transcription factors RELA, IRF1, ESR1, AR, POU5F1, TRIM28, and GATA1 with LOC441461 affected the degree of the malignancy of gastric cancer by modulating gene transcription." (PMID 35267457, 2022). "Functional analysis of TRIM28, EIF4A2, NAP1L1, PLD3, RPL18A, and TRPM7 suggested that they play direct roles in gastric cancer." (PMID 27835598, 2016). "However, in gastric cancer, TRIM28 suppressed CSC like characteristics via Wnt/β-catenin signaling and its knockdown enhanced the proliferation and clonogenic capacity of gastric cancer cells." (PMID 41303350, 2025). "Moreover, there was a positive correlation between lnc-TRIM28-14 and the expression of CD93 and COL4A1 in gastric cancer peritoneal metastasis, suggesting a regulatory relationship between them." (PMID 36690975, 2023). "Furthermore, lncRNA SNHG8 modulated several functional genes, including TRIM28, NAP1L1 and TRPM7 which affected downstream cancer pathways in gastric cancer." (PMID 30299268, 2018). "In gastric cancer (GC), using CRISPR–Cas9 genome-wide screening, TRIM28 is found to be the most significant regulator for PDL1 through directly binding to PDL1, preventing its ubiquitination, and promoting SUMOylation." (PMID 38609863, 2024).